SMO (smoothened, frizzled class receptor)
Diseases named in the same sentence as SMO in open-access papers (continued):
Sharing a sentence is not in itself a finding about the gene and the disease.
basal cell carcinoma (continued). "Vismodegib provides a remarkable therapeutic benefit to patients with advanced or metastatic basal cell carcinoma (BCC), a malignancy caused by loss of PTCH or mutational activation of SMO." (PMID 26784250, 2016). "For example, vismodegib is the first FDA-approved SMO inhibitor for the treatment of advanced and metastatic basal cell carcinoma." (PMID 26911235, 2016). "Targeting oncogenic HH/GLI signaling with small molecule inhibitors of the essential pathway effector Smoothened (SMO) has shown remarkable therapeutic effects in patients with advanced and metastatic basal cell carcinoma." (PMID 26784250, 2016). "These SMO alterations result in activation of Hedgehog signaling, another well-characterized pathway in cancer that is notably dysregulated in basal-cell carcinoma and medulloblastoma." (PMID 27458586, 2016). "Metastatic basal cell carcinomas are rare malignancies harbouring Hedgehog pathway alterations targetable by SMO antagonists (vismodegib/sonidegib)." (PMID 27942391, 2016). "GDC-0449 (Vismodegib) is approved for basal cell carcinoma therapy, and several SMO inhibitors including GDC-0449 are used in clinical investigations for SCLC." (PMID 28105432, 2016). "Experience in other histologies, particularly basal cell carcinoma, suggests the rapid development of resistance to single-agent SMO inhibitors." (PMID 26426053, 2015). "Unfortunately, resistance against currently used SMO inhibitors has already been observed in basal cell carcinoma (BCC) patients." (PMID 26053182, 2015). "Small molecule targeting of HH signaling by inhibiting the essential pathway effector Smoothened (SMO) has proven exceptionally efficient for the treatment of advanced and metastatic basal cell carcinoma." (PMID 25594066, 2014). "PTCH1 inactivation abolishes its negative regulation of the SMO oncogene and thus initiates the growth of multiple basal-cell carcinomas." (PMID 23548133, 2013). "Vismodegib as a SMO inhibitor has been used to treat basal cell carcinoma." (PMID 40836034, 2025). "Moreover, treatment of MB or basal cell carcinoma (BCC), another Hh pathway-driven cancer, with these inhibitors causes gene mutations, including SMO and its downstream molecules, in tumor cells, which results in drug resistance." (PMID 35725556, 2022). "Therefore, two SMO inhibitors (vismodegib and sonidegib) were approved for the treatment of basal cell carcinoma." (PMID 36209184, 2022). "Nevertheless, in several cancers including basal cell carcinoma (BCC) and medulloblastoma (MB), HH pathway is constitutively activated and related to ligand-independent mechanism, due to somatic mutations in PTCH1, SMO or SUFU genes." (PMID 34445078, 2021). "Basal cell carcinoma (BCC) is the most common human cancer, characterized by aberrant activation of the hedgehog (HH) signaling pathway resulting from mutations in the patched 1 (PTCH1) or smoothened (SMO) genes." (PMID 31756206, 2019). "All three SMO inhibitors are under investigation for treatment of solid tumors, and a known and approved antifungal drug itraconazole is being examined for potential clinical application for treatment of basal cell carcinoma." (PMID 30158435, 2018). "Interestingly, human MBs and basal cell carcinomas (BCCs) are frequently ciliated and abnormal activation of canonical HH signaling, through loss of the HH receptor PTCH1 or activation of SMO, is frequently found in human patients and is sufficient to induce these tumors in mice." (PMID 34638386, 2021). "While the contribution of non-canonical signaling in cancer has never been formally investigated, we propose that it may represent a novel therapeutic target for SMO inhibitors like vismodegib and sonidegib, approved for the treatment of advanced and metastatic basal cell carcinoma." (PMID 30148884, 2018). "Basal cell carcinoma (BCC), the most common human cancer, is driven by hyperactivation of Hedgehog Smoothened (SMO) and GLI transcription." (PMID 40060632, 2025).
basal cell carcinoma (continued). "Vismodegib (GDC-0449), another SMO inhibitor, was approved by the FDA to treat basal cell carcinoma." (PMID 32456660, 2020). "Sonidegib, an SMO antagonist, was approved by the FDA for the treatment of advanced basal cell carcinoma." (PMID 32456660, 2020). "In addition to SMO inhibitors like vismodegib and sonidegib, which are in clinical use for basal cell carcinoma, GLI1 inhibitors like GANT58 and GANT61 are in preclinical drug development and might be an effective mechanism to overcome drug resistance in breast cancer." (PMID 31394751, 2019). "Another FDA-approved SMO antagonist is NVP-LDE225 (Erismodegib or sonidegib), used for advanced cases of basal cell carcinomas." (PMID 31921137, 2019). "Vismodegib, a SMO antagonist, was the first Hh inhibitor to receive approval from the USA FDA in January 2012 for the treatment of locally advanced or metastatic basal cell carcinoma (BCC)." (PMID 26911235, 2016). "In mice, overexpression of SHH, activates SMO, GLI1 or GLI2 and promotes development of basal cell carcinoma like tumors." (PMID 23342114, 2013). "Inhibition of Smoothened (SMO), a key protein in the Hedgehog signaling pathway, is effective for locally advanced basal cell carcinoma (BCC), but is not yet used for sebaceous carcinoma (SEB) or squamous cell carcinoma (SCC)." (PMID 40542075, 2025). "To date, two SMO inhibitors (i.e. vismodegib, sonidegib) have been approved by the US Food and Drug Administration (FDA) and by the European Medicines Agency (EMA) for treating locally advanced basal cell carcinoma." (PMID 37476499, 2023). "Inhibition on SHH pathway through targeting SMO has been reported by using two novel SMO inhibitors in MB, Sonidegib (NVP‐LDE225, LDE) and Vismodegib (GDC‐0449, GDC), which have been approved by FDA in basal cell carcinoma and being examined in MB in clinical trials." (PMID 35419951, 2022). "Furthermore, SMO inhibitors like Vismodegib and Sonidegib have been approved by FDA for treatment of metastatic basal cell carcinoma." (PMID 31036836, 2019). "SMO is a molecular target of vismodegib, the first small-molecule hedgehog inhibitor to be approved by the FDA that has shown promise in the treatment of basal cell carcinomas." (PMID 31565188, 2019). "The SMO inhibitors vismodegib and sonidegib are FDA (food and drug administration) approved for the treatment of advanced, unresectable or metastatic basal cell carcinoma." (PMID 31394751, 2019). "To date, two SMO inhibitors (LDE225/Sonidegib and GDC-0449/Vismodegib) have received FDA approval for treating basal cell carcinoma while many clinical trials are being conducted to evaluate the efficacy of this exciting class of targeted therapy in a variety of cancers." (PMID 26891329, 2016). "Shh signaling, driven exclusively by PTCH1 that is SMO/GLI1-independent, includes induction of apoptosis in endothelial and neuroepithelial cells and regulation of the Cyclin B1/CDK1 pathway in basal cell carcinoma." (PMID 26545965, 2015). "Also, a nuclear localization of SMO, which drives GLI1 activation and is unresponsive to SMO inhibitors, has been reported to occur in Ptch1-silenced Basal Cell Carcinoma cells, again suggesting the activity of alternative non-canonical Hh-signaling." (PMID 31873117, 2019). "This implies that the SMO inhibitors, with two already approved by FDA for basal cell carcinoma treatment, will not be effective in sensitizing gastric cancer cells to chemotherapy." (PMID 28404967, 2017).
meningioma (102 papers, 2013 to 2025). A generally slow growing tumor attached to the dura mater. "For meningiomas with mutations in the Hedgehog (HH) pathway (SMO) or the NF2 pathway (FAK), targeted therapies such as vismodegib (an SMO inhibitor) and GSK2256098 (a FAK inhibitor) are being explored (NCT02523014)." (PMID 40787520, 2025). "Mutations in the gene Smoothened (SMO), which is involved in the hedgehog signaling pathway, are described in 3–5% of all meningiomas." (PMID 39273576, 2024). "Most non-NF2 gene meningiomas are usually caused by mutations in SMO (9%) and AKT1 (30%), especially in the cases where the meningioma is at the convexity at the skull-based, respectively." (PMID 39329938, 2024). "Meningiomas harboring recurrent somatic SMO mutations are part of a larger group of samples that exhibit activation of the Hedgehog (Hh) signaling pathway, which also includes cases with somatic biallelic loss of SUFU or PRKAR1AA17D mutation." (PMID 37805627, 2023). "For example, some meningiomas are found to have a highly expressed hedgehog signaling pathway, making somatic mutations of Smoothened (SMO) a potential target for chemotherapy." (PMID 36672431, 2023). "The SMO gene is yet another altered gene in grade I and II meningiomas whose mutations activate the Hedgehog signaling pathway." (PMID 38259646, 2023). "Collectively, our RNA-Seq results provide strong evidence for activation of Hh signaling among meningiomas that harbor relevant genomic mutations in SMO or PTCH1, or events near 2q35 or 7q36.3." (PMID 37805627, 2023). "We show that these samples exhibit activation of the Hh signaling pathway, similar to meningiomas with recurrent SMO mutations, using RNA-Seq and multiplexed immunofluorescence experiments." (PMID 37805627, 2023). "We found that meningiomas with predicted Hh signaling activating events (including recurrent SMO variants and structural events on 2q or 7q) exhibited robust staining of GAB1, a common clinical marker used to identify Hh pathway activation." (PMID 37805627, 2023). "Mutations in Nf2, TRAF7, KLF4, AKT1, and SMO are present in approximately 80% of sporadic meningiomas." (PMID 37898750, 2023). "Mutations in SMO have been detected in 3 to 6% of all meningiomas, 28% of olfactory groove meningiomas, and 11% of anterior skull base meningiomas." (PMID 36686824, 2022). "Subtotal surgical resection was performed, and histopathological diagnosis remained WHO grade 2 meningioma, this time with Ki-67 index of 24.8%, and SMO mutation detected on genomic sequencing." (PMID 35402234, 2022). "In validation cohorts, the AKT1 and SMO mutations were observed in skull base and higher grade meningiomas." (PMID 35402234, 2022). "Vismodegib, included in an ongoing Alliance clinical trial, is a hedgehog pathway-targeting agent tested for SMO/PTCH1-mutated progressive/recurrent meningiomas (NCT02523014)." (PMID 35712491, 2022). "Although the role of pharmacotherapy is currently ill-defined, a phase II trial is currently investigating the efficacy of targeted therapies in meningiomas harboring specific, targetable alterations, including SMO/AKT/NF2/CDK mutations (NCT02523014)." (PMID 35049691, 2022). "SMO mutations lead to cell-specific proliferation and mediate the development of meningioma through uncontrolled activation of the sonic hedgehog signaling pathway." (PMID 35712491, 2022). "Given the targetable nature of SMO mutations, a clinical trial is currently underway to test the SMO inhibitor vismodegib in SMO-mutant meningiomas." (PMID 36686824, 2022). "The SMO (L412F) mutations are usually found in midline meningiomas, probably due to the role of the Hedgehog pathway during hemisphere separation." (PMID 35892898, 2022). "NF2-altered tumors are mainly localized at the convexity or in the lateral and posterior skull base; SMO-mutated meningiomas arise in the olfactory groove, while those with AKT1 and PIK3CA mutations are mostly found in the anterior and middle skull base." (PMID 35049691, 2022).
meningioma (continued). "In their cohort of high grade meningiomas, most tumors were characterized by NF2 mutations, with very few tumors having mutations in TRAF7, KLF4, AKT1 and SMO, suggesting that high grade meningiomas have few targetable genetic mutations." (PMID 35402234, 2022). "Meningiomas with SMO or PTCH1 mutations were treated with vismodegib, an FDA-approved Hedgehog signaling pathway inhibitor." (PMID 35402234, 2022). "Meningiomas of the midline anterior skull base have been shown to harbor a variety of mutations but two are most common: missense mutations in SMO and the single activating mutation AKT1E17K." (PMID 34638590, 2021). "Two independent studies have identified TRAF7 (TNF receptor-associated factor 7), AKT1 (v-akt murine thymoma viral oncogene homolog 1), and SMO (Smoothened, frizzled family receptor) mutations as drivers of meningioma oncogenesis." (PMID 34300316, 2021). "Of tested olfactory groove meningiomas, approximately 28% harbor a SMO mutation compared to 3–5% at other intracranial locations." (PMID 33346248, 2020). "Multiple studies have shown SMO to be an independent mutation causing meningioma oncogenesis with an incidence of 3.6–6% of tested tumors." (PMID 33346248, 2020). "Clinical trials of Vismodegib and Afureserib, specific drugs for meningiomas with mutations in SMO and AKTl genes, are under way." (PMID 32974188, 2020). "AKT1 mutations result in downstream activation of the mTOR oncogenic pathway and SMO mutations cause activation of the Hedgehog signaling pathway rendering increased proliferation of meningioma cells." (PMID 32742192, 2020). "Of note, vismodegib has been included in current clinical trials on progressive meningioma (NCT02523014) in patients harboring SMO mutations." (PMID 31565188, 2019). "Mutations in the gene smoothened (SMO), which result in L412F or W535L substitutions lead to functional activation of Hedgehog signaling in meningioma." (PMID 31970090, 2019). "SMO mutations were identified in 11/71 (15.74%) cases in our cohort, leading to a characterized predisposition and vulnerability to meningioma formation." (PMID 31565188, 2019). "It is important to note that AKT1 and SMO mutations are selectively observed in a subset of non-NF2-mutated meningiomas (9% and 6% of cases, respectively); furthermore, PIK3CA mutations occurred in 7% of non-NF2-mutant meningiomas." (PMID 30279357, 2018). "Half of meningiomas that harbor SMO mutation are located in the anterior fossa and the remaining is located usually in the calvarium and median middle fossa similar to TRAF/AKT1 mutant meningiomas." (PMID 30082628, 2018). "Another group reported similar finding where olfactory groove meningiomas tend to have higher SMO mutation rates than meningiomas at other locations." (PMID 30082628, 2018). "SMO is encoding a negative regulator of the Hedgehog pathway and the mutations were found in 3%–5% of grade I meningiomas." (PMID 27429002, 2016). "Mutations in SMO or AKT1/TRAF7 are most frequently observed in meningiomas of the anterior cranial base." (PMID 27458586, 2016). "Meningiomas with SMO mutations generally follow a benign course." (PMID 40149634, 2025). "SMO, a G-coupled receptor, is important in the Hedgehog signaling pathway, which is crucial in promoting angiogenesis and tumor progression, and is linked with larger meningiomas and a higher recurrence rate than that in AKT1-mutated meningiomas." (PMID 39202270, 2024). "In addition, a study have suggested that SMO mutations are more frequent in grade I meningiomas than in grade II." (PMID 38259646, 2023). "However, while meningiomas with mutations in SMO and SUFU are more commonly associated with lower-grade histology, they have been found to have higher rates of recurrence, possibly related to bony invasion as evidenced by hyperostosis." (PMID 37010677, 2023).
meningioma (continued). "Furthermore, several disease-causing mutations, including NF2, TRAF7, KLF4, AKT1 and SMO, have been described in meningiomas and compounds specific for driver mutations are currently under investigation in clinical trials." (PMID 38102708, 2023). "Additionally, since inhibitors of this pathway hold great promise for the treatment of meningiomas harboring SMO mutations, ddPCR mutational analysis in tumor tissue has, once more, implications for targeted-individualized therapy in the SMO-mutated context." (PMID 38259646, 2023). "Meningiomas in the midline anterior skull base, along the olfactory groove or planum sphenoidale, typically harbor an underlying somatic mutation in one of the molecules involved in Hedgehog signaling, including SMO or SUFU." (PMID 37010677, 2023). "Among the non-NF2 mutant meningioma subgroup, mutations in SMO and SUFU were identified." (PMID 36010600, 2022). "SMO L412F and W535L mutations occur in approximately 5% meningiomas." (PMID 36010600, 2022). "For instance, an increased PD-L1 expression was found in TRAF7-mutated, compared with wild-type skull-base meningiomas, and an increased number of CTLA4+/CD3+ lymphocytes was found in grades 2 and 3 meningiomas harboring the PI3K–AKT–mTOR pathway or SMO mutations." (PMID 35565385, 2022). "Mutations in the SMO gene have also been associated with poor prognosis in grade I meningiomas." (PMID 35712492, 2022). "Furthermore, SMO mutations as well as mutations of other downstream regulator proteins have been shown to induce meningioma formation via disinhibition of the Sonic hedgehog signaling pathway." (PMID 34638590, 2021). "SMO mutations are seen in 3–5% of all meningiomas and display meningothelial histology." (PMID 33801089, 2021). "SMO-mutated meningiomas occur predominantly in the midline anterior skull base." (PMID 33262459, 2021). "Notably, only one meningioma with an SMO mutation had an anterior location; however, numerous tumors harboring KLF or POLR2A mutations had a central location." (PMID 33772057, 2021). "Conditional activation of SMO in developing mouse embryos resulted in the development of meningothelial meningiomas in the ventral skull base, with similar location and histological appearances to SMO-mutated meningioma." (PMID 33262459, 2021). "A clinical trial exploring the efficacy of the SMO inhibitor vismodegib in meningioma was initiated (NCT02523014), but vismodegib inhibits ciliary SMO, and it is unknown if meningiomas express primary cilia or encode the Hedgehog transcriptional program." (PMID 32690089, 2020). "While inactivating mutations in NF2 have been described in 30 to 60% of sporadic meningiomas, recent studies have shown that non-NF2 meningiomas harbor activating mutations in SMO (L412F and W535L), AKT1 (E17K), and KLF4 (K409Q), as well as inactivating mutations of TRAF7." (PMID 25347344, 2014). "Anterior parasagittal meningiomas are often driven by TRAF7, KLF4, or SMO mutations, while posterior ones are typically NF2-driven." (PMID 40569492, 2025). "TRAF7, SMO, AKT1, and KLF4 mutations, referred to as “non-NF2,” are typically found in lower-grade meningiomas, characterized by fewer chromosomal abnormalities, and generally result in better clinical outcomes." (PMID 40725113, 2025). "Key genetic drivers, including mutations in NF2, SMO, KLF4, TRAF7, and chromosomal aberrations, allow for the stratification of meningiomas into distinct molecular subtypes, each associated with unique clinical outcomes and therapeutic vulnerabilities." (PMID 39941893, 2025). "The molecular characterization of meningiomas has led to the identification of key tumor-driving mutations, including NF2, POLR2A, TRAF7, KLF4, AKT1, SMARCB1, SMARCE1, and SMO." (PMID 39941893, 2025).